LANCL2 (LanC like glutathione S-transferase 2)
Diseases named in the same sentence as LANCL2 in open-access papers:
LANCL2 is named in the same sentence as 36 diseases in open-access papers, as found by Europe PMC text mining. Sharing a sentence is not in itself a finding about the gene and the disease. The quoted sentences say what the papers report.
diabetes (7 papers, 2015 to 2023). "Several studies explored LANCL2 activation as a validated pharmacological target for diabetes and inflammatory bowel disease." (PMID 38140095, 2023). "LANCL2 is highly expressed in the brain and has recently emerged as a therapeutic target for inflammatory diseases and diabetes." (PMID 33182586, 2020). "Specifically, studies including individuals with metabolic disorders, such as IGT, diabetes, or obesity, will help characterize the efficacy and engagement of LANCL2 by ABA in the target tissue." (PMID 31370154, 2019). "The potential role of LANCL2 as a new drug target in diabetes has already been suggested and efforts at discovering LANCL2-targeting drugs are underway." (PMID 28660193, 2017). "The potential role of LANCL2 as a new drug target in diabetes has been also suggested by other authors and efforts at discovering LANCL2-targeting drugs have been reported." (PMID 26488296, 2015). "The increased muscle expression of LANCL1 in LANCL2 KO mice as compared with wild-type siblings may explain why LANCL2 KO mice with streptozotocin (STZ)-induced diabetes indeed respond to ABA similarly to, or perhaps even better than, wild-type mice." (PMID 36674711, 2023). "At the end point of a similar protocol of ABA-pretreatment followed by diabetes induction with low-dose STZ, the mean glycemia of LANCL2 KO mice was significantly lower than that of wild-type animals." (PMID 36674711, 2023). "The increased muscle expression of LANCL1 in LANCL2 KO mice, as compared with WT siblings, may explain why LANCL2 KO mice with STZ-induced diabetes respond to ABA similarly to, or perhaps even better than, WT mice." (PMID 35736456, 2022).
glioblastoma (4 papers, 2018 to 2022). The most malignant astrocytic tumor (WHO grade IV). "Our findings suggest that amplification of LANCL2 and EGFR were the independent diagnostic biomarkers for glioblastoma patients, and LANCL2 amplification was a significant prognostic factor for OS in younger glioblastoma patients." (PMID 34461927, 2021). "Multivariate analysis showed that LANCL2 amplification was significantly correlated with reduced OS in younger (< 60 yrs) glioblastoma patients of TCGA database and our tumor banks." (PMID 34461927, 2021). "Amplification of these co-located genes at 7p11 has also been described in glioblastoma, with LANCL2 amplification portending a poor prognosis in younger glioblastoma patients." (PMID 34912708, 2021). "Taken together, amplification of LANCL2 and EGFR were the independent diagnostic biomarkers for glioblastoma patients, and LANCL2 amplification was a significant prognostic factor for OS in younger glioblastoma patients." (PMID 34461927, 2021). "Multivariate analysis showed that LANCL2 amplification was significantly correlated with reduced overall survival (OS) in younger (< 60 years) glioblastoma patients of TCGA database (p = 0.043, HR = 1.657) and our tumor banks (p = 0.018, HR = 2.199)." (PMID 34461927, 2021). "Glioblastoma, head and neck squamous cell carcinoma, esophagogastric adenocarcinoma and non-small cell lung cancer were the top four tumors with the highest alteration frequencies of LANCL2 and EGFR." (PMID 34461927, 2021). "LanCL2 overexpression was correlated with glioblastoma recurrence, and its activation may trigger its translocation into the nucleus." (PMID 34461927, 2021). "Epidermal growth factor receptor (EGFR) and lanthionine synthetase C-like 2 (LanCL2) genes locate in the same amplicon, and co-amplification of EGFR and LANCL2 is frequent in glioblastoma." (PMID 34461927, 2021). "The amplification of LANCL2 or EGFR, and their co-amplification were frequent in glioblastoma of TCGA database and our tumor banks." (PMID 34461927, 2021). "Taken together, amplification and mRNA overexpression of LANCL2 and EGFR, and their co-amplification and co-expression were frequent in glioblastoma patients." (PMID 34461927, 2021). "VSTM2A, LANCL2, SEC61G and VOPP1 were also amplified and are reported in the literature as fusion genes with EGFR in some glioblastoma patients." (PMID 29844869, 2018). "mRNA and protein overexpression of LANCL2 and EGFR was also frequently found in glioblastoma." (PMID 34461927, 2021). "However, mRNA or protein expression of EGFR and LANCL2 was not significantly correlated with OS of glioblastoma patients." (PMID 34461927, 2021). "However, the prognostic value of LANCL2 and EGFR co-amplification, and their mRNA and protein expression in glioblastoma remain unclear yet." (PMID 34461927, 2021). "The protein expression level of LANCL2, rather than EGFR, was elevated in relapsing glioblastoma, compared with newly diagnosed glioblastoma." (PMID 34461927, 2021). "However, LANCL2 or EGFR amplification, and their co-amplification had no significant impact on OS in older (≥ 60 years) or IDH1/2-wild-type glioblastoma patients." (PMID 34461927, 2021).
inflammatory bowel disease (3 papers, 2021 to 2023). A spectrum of small and large bowel inflammatory diseases of unknown etiology. "Accordingly, LANCL2 was, so far, investigated as a promising target for chronic inflammatory, metabolic, and immune-mediated diseases, such as inflammatory bowel disease (IBD), and cancer." (PMID 38140095, 2023). "Activation of the LANCL2 pathway in the gut through oral omilancor treatment has demonstrated therapeutic efficacy in 6 different preclinical models of inflammatory bowel disease (IBD)." (PMID 34615968, 2021).
atherosclerosis (2 papers, 2018 to 2025). A disease characterized by the build-up of fatty material and calcium deposition in the arterial wall resulting in partial or complete occlusion of the arterial lumen. "Whatever the role of abscisic acid in the atherosclerotic plaque is, its function in inflammation (and presumably atherosclerosis) is mediated by LANCL2." (PMID 29665821, 2018).
asthma (1 paper, 2021). "Interestingly, we observed significantly reduced expressions of LancL2 and PPAR-γ on PBMC from asthma patients compared to the normal controls." (PMID 34169084, 2021).
astrocytoma (1 paper, 2021). "Among the LGG data, the amplification frequencies of LANCL2 and EGFR in astrocytoma were the highest (7.33% and 13.92%, respectively), while those in oligoastrocytoma were the lowest (1.07% and 1.60%, respectively)." (PMID 34461927, 2021). "However, the mRNA overexpression frequencies of LANCL2 and EGFR in LGG samples were only around 10%, and little difference was shown in astrocytoma, oligoastrocytoma and oligodendroglioma." (PMID 34461927, 2021).
clear cell renal cell carcinoma (1 paper, 2021). "Among them, LGG, testicular germ cell carcinoma, GBM and uveal melanoma were the top four tumors with the highest average mRNA expression of LANCL2, while the average mRNA expression of EGFR was highest in GBM, head and neck cancer, clear cell renal cell carcinoma (ccRCC) and LGG." (PMID 34461927, 2021).
glioma (1 paper, 2021). A benign or malignant brain and spinal cord tumor that arises from glial cells (astrocytes, oligodendrocytes, ependymal cells). "The protein expression level and intracellular localization of LanCL2 were correlated with the grade of gliomas." (PMID 34461927, 2021). "Since the co-amplification of LANCL2 and EGFR was found in GBM in 2002, studies of LANCL2 are barely reported in glioma till now." (PMID 34461927, 2021). "Here, our immunohistochemical result found that the expression and localization of LanCL2 was correlated with the grade of gliomas." (PMID 34461927, 2021). "The higher the glioma grade, the higher the expression intensity of LanCL2." (PMID 34461927, 2021). "LanCL2 was expressed in both the normal brain tissues and gliomas." (PMID 34461927, 2021). "The amplification frequencies of LANCL2 and EGFR in GBM were up to 27.65% (159 of 575 cases) and 44.35% (255 of 575 cases), whereas those in low-grade glioma (LGG) were only 3.91% (20 of 511 cases) and 7.63% (39 of 511 cases), respectively." (PMID 34461927, 2021). "LanCL2 was mainly found in the nucleus and cytoplasm of high-grade glioma cells (grade III–IV), whereas it was expressed on the nuclear membrane of low-grade (grade I–II) glioma cells." (PMID 34461927, 2021). "In addition, the amplification frequencies of LANCL2 and EGFR in GBM were six to nine times higher than those in grade II-III gliomas." (PMID 34461927, 2021). "In addition, the intracellular localization of LanCL2, not EGFR, was associated with the grade of gliomas." (PMID 34461927, 2021). "Results showed that compared with the copy numbers in normal brain tissues and grade I gliomas, the copy numbers of EGFR were significantly elevated in GBM, while the copy numbers of LANCL2 had no obvious changes." (PMID 34461927, 2021).
Hyperglycemia (1 paper, 2022). An increased concentration of glucose in the blood. "LANCL2 KO mice spontaneously overexpress LANCL1 in the SkM (approx. twice the amount of their WT siblings), allowing us to test whether LANCL1 could mediate the beneficial effect of chronic ABA treatment on hyperglycemia induced by low-dose STZ." (PMID 35736456, 2022).
Hyperkeratosis (1 paper, 2021). Hyperkeratosis is a histopathological term defining a thickened stratum corneum and may be present in many different skin conditions, with many possible overlaps. "Skin LANCL2 activation through topical omilancor treatment reduced both epidermal hyperplasia and hyperkeratosis when compared to the untreated group." (PMID 34615968, 2021).
influenza (1 paper, 2017). An acute viral infection of the respiratory tract, occurring in isolated cases, in epidemics, or in pandemics; it is caused by serologically different strains of viruses (influenzaviruses) designated A, B, and C, has a 3-day incubation period, and usually lasts for 3 to 10 days. "By using pharmacologic activation of LANCL2 and loss-of-function approaches in knockout mice, we validate the LANCL2 pathway as a putative target for the treatment of influenza infection." (PMID 28270815, 2017). "In NSC61610-treated wild-type mice, oral treatment of NSC61610 increases expression of LANCL2 throughout the time course of influenza infection." (PMID 28270815, 2017). "After observation of the importance of LANCL2 in the resolution phase of infection, we sought to identify if novel ligands of LANCL2 could aid in the response to influenza." (PMID 28270815, 2017). "Moreover, oral administration of ABA as a pre- and post-exposure therapeutic upregulates LANCL2 expression in the lungs of influenza-infected mice, reduces influenza virus-related immunopathology, and accelerates recovery in infected mice." (PMID 28270815, 2017).
laryngeal carcinoma (1 paper, 2019). Carcinoma that arises from the laryngeal epithelium. "The prognosis of laryngeal cancers could be improved by addition of markers such as IL1RAP, LANCL2, RYK, and SLC33A1." (PMID 31310629, 2019).
lung adenocarcinoma (1 paper, 2021). A carcinoma that arises from the lung and is characterized by the presence of malignant glandular epithelial cells. "In silico clinical correlation analysis using the Cancer Genome Atlas Lung Adenocarcinoma dataset revealed a positive correlation between LANCL2 and EGFR expression and an inverse relationship between LANCL2 gain-of-function and survival in LUAD patients." (PMID 33568630, 2021).
memory impairment (1 paper, 2020). "Taken together, our results indicate that ABA reduced Aβ deposition, neuroinflammation, and memory impairment, which is the most characteristic pathology of AD, via the upregulation of LANCL2." (PMID 33182586, 2020).
prostate carcinoma (1 paper, 2025). A carcinoma that arises from epithelial cells of the prostate gland. "Furthermore, a study has shown that ABA can promote quiescence via LANCL2- and PPARγ-induced MAPK activation in prostate cancer." (PMID 41009037, 2025).
tumor (6 papers, 2010 to 2023). "A nude murine PC9 xenograft tumor model was constructed to assess whether the loss or rescue of LANCL2 expression affects the growth of EGFR-mutant LUAD xenograft tumors in vivo." (PMID 33568630, 2021). "We tracked tumor growth for 6 weeks and noted LANCL2-KD + OE-NC tumors grew slower than control LANCL2-NC + OE-NC tumors, while LANCL2-OE rescued this effect." (PMID 33568630, 2021). "Multivariate analysis of samples from both TCGA database and our tumor banks demonstrated that LANCL2 amplification was a significant independent prognostic factor for OS in younger GBM patients." (PMID 34461927, 2021). "Univariate analysis of TCGA database and our tumor banks showed that amplification of LANCL2 or EGFR, and their co-amplification were significantly correlated with poor OS, but not PFS of GBM patients." (PMID 34461927, 2021). "LANCL2-OE rescued the decreased tumor size and weight produced by LANCL2-KD." (PMID 33568630, 2021). "LANCL2 knockdown reduced proliferation and enhanced apoptosis in PC9, HCC827, and A549 cells in vitro and suppressed murine PC9 xenograft tumor growth in vivo." (PMID 33568630, 2021). "Nevertheless, the results obtained with tumours arboring different copy numbers of the EGFR, SEC61G, LANCL2 and VOOP1 genes allow us to establish that mRNA over-expression parallels the level of amplification." (PMID 21170331, 2010). "Moreover, LUAD tumor LANCL2 mRNA expression and LUAD tumor EGFR mRNA expression displayed a strong positive correlation (Pearson r = 0.63)." (PMID 33568630, 2021). "Additionally, the shRNA-mediated knockdown of LANCL2 reduced proliferation and enhanced apoptosis in the EGFR-mutant LUAD cell lines PC9 and HCC827 in vitro and suppressed PC9 xenograft tumor growth in vivo." (PMID 33568630, 2021). "Here, this study analyzed the copy number variations (CNVs), mRNA and protein expression profiles, and their prognostic values of LANCL2 and EGFR in GBM specimens from TCGA database or from the tumor banks of Shenzhen Second People’s Hospital and Sun Yat-sen University Cancer Center." (PMID 34461927, 2021). "Two genes (LANCL2 and VOPP1) and SEPT14 were respectively amplified in 3 and 2 tumours." (PMID 21170331, 2010). "However, probably due to a smaller sample size of GBM patients, age and gender had no significant impact on the OS of GBM patients from our tumor banks, leading that LANCL2 amplification was a significant independent prognostic factor for OS in multivariate analysis." (PMID 34461927, 2021). "In our tumor banks, we found that the protein expression of EGFR was elevated in GBM samples, whereas LanCL2 expression did not significantly change." (PMID 34461927, 2021).
infection (5 papers, 2016 to 2022). The state of being infected such as from the introduction of a foreign agent such as serum, vaccine, antigenic substance or organism. "Following infection, the overexpression of LANCL2 in PC9 cells was confirmed using qPCR and immunoblotting." (PMID 33568630, 2021). "Following infection, the knockdown and overexpression of LANCL2 in LANCL2-KD + OE-NC and LANCL2-KD + OE cells, respectively, was confirmed using qPCR and immunoblotting in PC9 cells." (PMID 33568630, 2021). "Within the lungs of infected mice, LANCL2−/− possessed lower levels of IL-10 and higher levels of IL-6 at day 12 post-infection." (PMID 28270815, 2017). "We provide molecular evidence in vivo that NSC61610 functions in a LANCL2-dependent manner during the recovery phase of infection, since the beneficial effects of NSC61610 treatment observed in wild-type mice are abrogated in LANCL2 knockout mice." (PMID 28270815, 2017). "A significant reduction in CX3CR1+ IL10-producing macrophages, the in vivo analog of the Mreg species, at three weeks post infection was observed, resulting in a decrease to 50% of wild-type levels in LANCL2-/- mice." (PMID 27936058, 2016). "LANCL2−/− mice also showed lesser numbers of tissue repair and homeostasis cell types in alveolar macrophages and type 2 innate lymphoid cells at day 12 post-infection while displaying greater number of neutrophils at day 7 post-infection." (PMID 28270815, 2017). "The increased expression of amphiregulin with LANCL2 activation may be a key component in the reduction of epithelial necrosis and lung damage during infection." (PMID 28270815, 2017). "The ability of LANCL2 activation to promote a regulatory, IL-10-producing, macrophage population suggests efficacy of this pathway to control the damaging effects of the influenza virus in the lungs throughout the course of infection." (PMID 28270815, 2017). "Indeed, LANCL2-/- mice showed even greater reduction in H. pylori burden at three weeks post infection compared to the LANCL2Myeloid KO strain, suggesting additional LANCL2 epithelial and/or T cell intrinsic contributions to the regulatory environment of the mucosa." (PMID 27936058, 2016). "Given the dual roles of LANCL2 and the increasing importance of metabolism on regulating immune signaling, modeling LANCL2 effect on CD4+ T cell differentiation during infection such as CDI may prove to be valuable in defining new therapeutic opportunities." (PMID 36418318, 2022). "This suggests that, while MDSCs may assist in the resolution of infection, IL-10-producing cells are the critical effectors of NSC61610 treatment and LANCL2 activation." (PMID 28270815, 2017).
cancer (3 papers, 2019 to 2021). A tumor composed of atypical neoplastic, often pleomorphic cells that invade other tissues. "Results showed that the dominant genomic alterations of LANCL2 and EGFR in cancers were amplification and mutation, while gene fusion and deep deletion were rare." (PMID 34461927, 2021). "Pathway analysis and co-immunoprecipitation followed by mass spectrometry of differentially-expressed genes in LANCL2 knockdown cells revealed enrichment of several cancer signaling pathways." (PMID 33568630, 2021). "Furthermore, pathway analyses of DEGs from LANCL2 knockdown revealed significant enrichment for several cancer signaling pathways in PC9 cells." (PMID 33568630, 2021). "Firstly, to investigate the CNVs of LANCL2 and EGFR genes in a panel of cancers, 32 studies of different cancer types in TCGA Pan-Cancer Atlas database (n = 10,967) were selected." (PMID 34461927, 2021). "The mRNA expression profiles of LANCL2 and EGFR were investigated in 32 different cancers of TCGA database." (PMID 34461927, 2021).
LANCL2 also shares sentences with these, for which no sentence is quoted: metabolic disorders (2 papers); adenocarcinoma (1); autoimmune disease (1); breast adenocarcinoma (1); colitis (1); degenerative diseases (1); esophagogastric adenocarcinoma (1); head and neck cancer (1); head and neck squamous cell carcinoma (1); inflammatory skin disorders (1); non-small cell lung carcinoma (1); Obesity (1); oligoastrocytoma (1); oligodendroglioma (1); oral cancer (1); psoriasis (1); respiratory diseases (1); uveal melanoma (1).